TNF (tumor necrosis factor)
Diseases named in the same sentence as TNF in open-access papers (continued):
Sharing a sentence is not in itself a finding about the gene and the disease.
Arthritis (continued). "Treatment of arthritis in mice with antibodies against these proinflammatory cytokines TNF-α and IL-6 has been shown to attenuate the disease." (PMID 35924250, 2022). "T cell trafficking and proinflammatory cytokines such as TNF-α, IL-1β, IL-6, and MMPs are reduced when IL-7 is blocked, which lowers joint inflammation." (PMID 35368757, 2022). "Various inflammatory cytokines are known to contribute to the bone erosion in arthritis, including IL-1, IL-6, and tumor necrosis factor (TNF)." (PMID 35464401, 2022). "The Tg197 human TNF transgenic mice constitutively produced human TNFα, and then spontaneously developed severe arthritis." (PMID 35273620, 2022). "In a mouse model of PGRN-deficient arthritis, PGRN inhibits the binding of TNF to its receptor and blocks intracellular signaling pathways." (PMID 35880418, 2022). "The results showed that CM, reduced the migration of inflammatory cells to the intestinal tract and arthritis index by reducing the concentration of TNF-α." (PMID 35493477, 2022). "NPnon-targeted treatment suppressed pro-inflammatory cytokines IL-6 by 73.3% when compared to arthritis control (p-value: 0.03); TNF-α by 42% p-value: 0.002; IL-17A by 70.6%, p-value: 0.05; and IFN-γ by 61.3%, p-value: 0.03) pg/mL." (PMID 36241847, 2022). "Previous studies have shown that ellagic acid alleviated the adjuvant-induced arthritis model in mice by modulation of pro-and anti-inflammatory cytokines (IL-1β, TNF-α, IL-17, IL-10, and IFN-γ)." (PMID 35130279, 2022). "Blocking TNF-α provided both protective and therapeutic effects against arthritis in DNase II−/−Ifnar1−/− mice." (PMID 34901991, 2022). "We also observed a concomitant increase in the levels of many cytokines, including IL-1β, IL-6, TNF-α, and IL-1α, in knee homogenates in WT mice after arthritis induction." (PMID 35439173, 2022). "The 8–9-month-old TNF-Tg mice used in this study were confirmed to have severe arthritis in their ankles afferent to the PLVs by μCT with significantly reduced talus bone volumes (WT 1.39 ± 0.07 vs TNF-Tg 0.49 ± 0.12 mm3, p < 0.0001; Supp." (PMID 35255954, 2022). "Lastly, low dose IKE together with etanercept, a TNF antagonist, induce ferroptosis in fibroblasts and attenuate arthritis progression in the CIA model." (PMID 35115492, 2022). "Another study demonstrated the involvement of the Toll-like receptor 4 pathway and the beneficial use of the TNF-α antagonist infliximab for the treatment of joint inflammation in MPS VI." (PMID 36556450, 2022). "Mice with TNF-α induced arthritis were found to have increased circulation of osteoclast precursors which was reversed by anti-TNF-α therapy and correlated with systemically increased TNF-α concentrations." (PMID 35927754, 2022). "It is well known that the secretion of TNF-α is regulated by NF-κB p65, and TNF-α, which is more prominent than other inflammatory factors, is also known to influence arthritis." (PMID 35057057, 2022). "They found that TNF-α antagonists combined with ferroptosis inducers enhanced ferroptosis in fibroblasts and improved arthritis progression in collagen-induced arthritis mice." (PMID 35835748, 2022). "Together, these results suggest that the expansion of the S2b-S2a-S2d-S4b-S4a branch upon TNF expression commands arthritis development and influences cell fate choices via specific sets of pathogenesis induced genes." (PMID 35879783, 2022). "huTNFTg mice spontaneously develop arthritis and have previously been used to investigate the role of systemic TNF overexpression in different inflammation-driven pathologies." (PMID 36307458, 2022). "A collagen-induced murine arthritis model study with additional IL-34 injection led to increased TNF-α and IL-17 mRNA expression in the synovial tissues, indicating a proinflammatory role for IL-34 via IL-17 production entailing aggravation of arthritis." (PMID 36530919, 2022).
Arthritis (continued). "ApoB was reported to aggravate arthritis by eliciting the production of TNF-α, IL-1β, and IL-6 through p38 mitogen-activated protein kinase and NF-κB pathways." (PMID 34996506, 2022). "For instance, mice with TNF-α induced arthritis and possessed increased osteoclast precursors in serum, and subsequently was reversed by anti-TNF-α therapy and correlated with systemically increased TNF-α concentrations." (PMID 35369099, 2022). "For patients with advanced retinal degeneration, TNF inhibitors and IL-1 inhibitors can be considered for treatment of non-ocular disease manifestations including fevers, headaches, and arthritis." (PMID 35868845, 2022). "Swelling of the hind paws indicative of arthritis decreased significantly compared to the vehicle treated group for the anti-TNF monotherapy (p = 0.006), anti-IL-17A monotherapy (p = 0.011) and the dual blockade therapy groups (p = 0.008)." (PMID 35055042, 2022). "On the other hand, etanercept (a TNF inhibitor) treatment delayed the appearance of spondylitis and arthritis and suppressed arthritis severity, evidencing a role of TNF and innate immune activation in the induction phase in this SpA animal model." (PMID 35464438, 2022). "Several studies have reported that C-reactive protein (CRP), leukotriene B4 (LTB4), prostaglandin E2 (PGE2), interleukin 6 (IL-6), and tumor necrosis factor-alpha (TNF-α) play crucial roles in inflammatory processes and the pathophysiology of arthritis." (PMID 36046031, 2022). "The combination of a TNF antagonist and a low dose of ferroptosis inducer induces ferroptosis in synovial fibroblasts and markedly attenuates arthritis progression in the CIA model." (PMID 35115492, 2022). "Panel D-F, both SAP (the murine counterpart of CRP), IL-6 and TNF-α were significantly elevated after induction of arthritis." (PMID 35077491, 2022). "It would be plausible that inflammatory stimuli such as TNF-α, IL-1, and IL-6, all induced during K/B×N serum–transferred arthritis, promote sPLA2-IIA expression in these leukocytes, leading to increased circulating sPLA2-IIA concentrations in this model." (PMID 35076027, 2022). "Here the authors use a mouse RA model, single cell RNA sequencing and in vitro analyses to show that inducing ferroptosis and suppressing TNF signaling reduce fibroblast numbers and ameliorate experimental arthritis." (PMID 35115492, 2022). "It is a critical mediator of tumor necrosis factor alpha (TNF)-induced transformation of fibroblast-like s-ynoviocytes (FLS) in arthritis." (PMID 35529852, 2022). "Using the adjuvant-induced arthritis (AIA) model in rats, the positive effect of local cryotherapy on arthritis severity and joint damage was shown to be IL-6/IL-17A-driven but TNF-α independent." (PMID 35488311, 2022). "Topical arthritis is mainly brought by synovium and synovial fluid via synthesizing and releasing inflammatory factors (IL-1, IL-6, TNF) and MMPs." (PMID 36032667, 2022). "In a rat model of arthritis induced by type II collagen and treated with DAPs, IL-1β, IL-2, IL-6, TNF-α, IFN-γ, and dihydroorotate dehydrogenase (DHO-DHase) were inhibited." (PMID 36235835, 2022). "PQQ has anti-inflammatory effects and can reduce arthritis by inhibiting the production of pro-inflammatory cytokines such as TNF-α and IL-6." (PMID 35592257, 2022). "In this study we investigated the suppressant effect of ozoralizumab and adalimumab, an anti-TNFα IgG, on arthritis and induction of ADAs in human TNF transgenic mice." (PMID 35273620, 2022). "Here we investigated the anti-arthritic efficacy of ozoralizumab in a human TNF transgenic mouse and attempted to predict clinical benefit of ozoralizumab for treatment of TNFα-induced arthritis." (PMID 35273620, 2022). "We found that injection with ICI induced severe arthritis and pneumonitis in the mice, severer diseases in the mice that had been injected with CA, accompanied by a higher frequency of TNF-α+ T cells in the mice." (PMID 36016934, 2022).
Arthritis (continued). "The herbal medicine, formic acid, prevents TNF-induced LEC NO, restores LV contractions, and attenuates arthritis in TNF-Tg mice." (PMID 33602317, 2021). "Several cytokines are responsible for arthritis, such as IL-1b, TNF-α, IL-1β, IL-6 and IFN-γ of dendritic cells, T cells and macrophages, respectively." (PMID 34959384, 2021). "For example, macrophages are activated by pro-inflammatory factors such as interleukin (IL)-1β and tumor necrosis factor (TNF)-α under oxidative stress to produce superoxides, in turn accelerating the development of arthritis." (PMID 33897428, 2021). "The upregulation of tumor necrosis factor-alpha (TNF-α) is a common event in arthritis, and the subsequent signaling cascade that leads to tissue damage has become the research focus." (PMID 34943075, 2021). "In arthritis, higher expression of inflammatory molecules (interleukins and TNF-α) activates the NF-кB inflammatory pathway which results in the disease progression." (PMID 34646138, 2021). "The data from our whole-mount staining revealed significantly reduced lymphatic vessels covered by LMCs in TNF-Tg mice with severe arthritis." (PMID 33602317, 2021). "In this study, we found that 18β-GA, especially 18β-GA combined with MTX, dramatically reduced collagen-induced arthritis as well as TNF-α- and LPS-induced cell inflammation." (PMID 34381358, 2021). "It was also shown that TNF produced by myeloid cells controls arthritis onset by regulating the activation of synovial fibroblasts, and that B cell-derived TNF regulates the severity of arthritis through induction of autoantibodies." (PMID 34681582, 2021). "This study showed that the administration of curcumin reduced arthritis symptoms such as joint stiffness, hyperalgesia, oxidative stress, and TNF-α levels, improved mobility, expression of biochemical markers, and had the joint-protective potential." (PMID 33478498, 2021). "ACRH was previously shown to inhibit TNF-α and IL-1β, as demonstrated in adjuvant-induced arthritis in rat." (PMID 34172047, 2021). "The in vivo activity was evaluated using parameters like COX, TNF-α and IL-6 inhibition assay and arthritis score in Freund Adjuvant (CFA) models at a dose of 400 mg/kg b.w. per day of different fractions (hexane, chloroform, alcoholic)." (PMID 33919084, 2021). "The successful use of anti-TNF for the treatment of ICI-induced arthritis suggests a possible role of TNF in irAE pathogenesis." (PMID 35126126, 2021). "In particular, inhibition of IL1, IL-6, and TNF have been reported to be highly effective in suppressing arthritis." (PMID 35008766, 2021). "Visual inspection and biochemical examinations including TNF-α, interleukin 6, and C-reactive protein were performed to assess arthritis severity during the treatment." (PMID 34880764, 2021). "It has been reported that IL-18 expression in synovial tissue correlates with the severity of joint inflammation and the levels of TNF-α and IL-1β." (PMID 34681582, 2021). "We investigated the effect of the Tyrosine Kinase inhibitors (TKIs) dasatinib and bosutinib, on the human TNF-dependent Tg197 arthritis mouse model." (PMID 33892739, 2021). "In this study, rats with CIA were successfully developed and subsequently, the levels of TNF-α and IL-6 in rats significantly improved and pathological changes on arthritis obviously displayed." (PMID 34880764, 2021). "In fact, in a TNFα-induced model of arthritis, genetic deletion of PAD2 resulted in amelioration of joint inflammation, demonstrating the connection between PAD2 activity and TNFα-mediated destruction in another disease context." (PMID 34961522, 2021). "Conversely, by targeting ADAM17, there is an overexpression of TIMP-3 dampened TNF-release that ameliorated the development of arthritis in a murine model of the disease." (PMID 33673623, 2021). "The authors concluded that anti-TNF therapy is favorable for both rheumatic joints but also for the periodontal tissues of arthritis-affected subjects." (PMID 33546101, 2021).
Arthritis (continued). "Mice with TNF-α induced arthritis were found to have increased circulation of osteoclast precursors." (PMID 34620220, 2021). "In a serum‐transfer murine model of arthritis, pro‐inflammatory cytkoines including TNF‐α and IL‐6 are present in the joint." (PMID 32955748, 2021). "Consistent with the results of the bioenergetic analysis, measurement of mitochondrial linearity also revealed that the FLS from resolving arthritis patients demonstrated the greatest degree of plasticity in response to TNFα stimulation." (PMID 34512657, 2021). "Our data demonstrate that TNFR1 inhibition through Atrosimab administration efficiently blocked TNFR1-mediated inflammatory responses in a model of acute TNF-mediated inflammation and in experimental arthritis, NASH and EAE." (PMID 34305946, 2021). "In our TNF-Tg mouse arthritis model, we found that the remission of arthritis due to Haidalimumab treatment was comparable to that of Humira in both moderate arthritis model and or severe arthritis model." (PMID 34886761, 2021). "Nonetheless, PAD2 is probably required for the transition of B cells to plasma cells, as the knockout of Pad2 can cause a significant reduction in bone marrow plasma cells in a mouse model of TNF- α induced arthritis." (PMID 34804050, 2021). "The mean arthritis score and the levels of inflammatory cytokines, including TNF-α, were significantly lower in rats treated with delanzomib and adalimumab than in those treated with either delanzomib or adalimumab." (PMID 34880764, 2021). "Experimental studies on animal models of arthritis have indicated a positive effect of TNF-α inhibition on bone metabolism." (PMID 34055540, 2021). "5XFAD/Tg197 AD/TNF double-transgenic mice develop a human TNF-α (huTNF-α) expression induced Aβ plaques deposition and arthritis." (PMID 34067173, 2021). "On the other hand, treatment of the mice with anti-IFN-γ monoclonal antibodies attenuated the severity and frequency of arthritis due to lower levels of serum TNF-α, IL-6, and IL-1β." (PMID 33546401, 2021). "Activation of p38 mitogen-activated protein kinase (MAPK) is crucial in TNF-α-related arthritis, and the p38 MAPK/NF-kB axis has been shown to mediate the inflammatory response in chondrocytes." (PMID 34943075, 2021). "HSP72 expression has been shown to exhibit increased levels in collagen-induced arthritis mouse model and recombinant HSP72 which markedly inhibits the expression of IL-6, TNF-α and NF-κB, highlighting its protective role in arthritis." (PMID 34053448, 2021). "In patients with S. aureus arthritis, the levels of TNF-α have been shown to be highly elevated in the synovial fluid." (PMID 33546401, 2021). "During arthritis, TNF-α, and other inflammation factors continuously stimulate the osteoblasts to produce RANKL, which leads to osteoclast genesis by interacting with RANK located on the osteoclast." (PMID 33748207, 2021). "Tripterygium glycosides tablets have been indicated to reduce the inflammatory response in rat lung tissue; it can upregulate IL-10 expression and TNF-α levels in the rat arthritis model." (PMID 34721642, 2021). "Numerous studies have indicated that TNFα playsa critical role, not only during the pathogenesis ofinflammatory arthritis but also during degenerativejoint disease like OA." (PMID 32347037, 2021). "Long-term TNF blockade reduced cardiovascular incidents in several observational studies of patients with arthritis." (PMID 33800271, 2021). "TQ (5 mg/kg body weight) significantly downregulated the level of pro-inflammatory mediators (IL-1b, IL-6, TNF-α, and prostaglandin E2) to reduce arthritis scoring and bone leaching in collagen-induced arthritis in a Wistar rats in vivo model." (PMID 34067322, 2021). "Our findings show that dasatinib exhibits a therapeutic effect in TNF-driven arthritis and can act in synergy with a subtherapeutic anti-hTNF dose to effectively treat the clinical and histopathological signs of the pathology." (PMID 33892739, 2021).
Arthritis (continued). "We further investigated the possible synergistic effect of 30 mg/Kg dasatinib in combination with additional anti-TNF agents, that in high-dose monotherapies ameliorate arthritis." (PMID 33892739, 2021). "In order to verify the contribution of LMCs to the progression of arthritis, it is important to compare the phenotype observed in LMCs isolated from both WT and TNF-Tg mice and know if these LMCs from TNF-Tg mice play a role in inflammation." (PMID 33602317, 2021). "The release of pro-inflammatory cytokines such as TNF-α, IL-1β, IL-33, and the process of NETosis are widely known to aggravate arthritis disease status and pain." (PMID 34539449, 2021). "We therefore first compared the therapeutic activity of Atrosimab to anti-TNF drugs using a model of experimental arthritis using Tg197hTNFR1KI transgenic mice." (PMID 34305946, 2021). "Impact of ADAs on disease outcomes in children and adults withinflammatory arthritis treated with anti TNF-α agents." (PMID 34188697, 2021). "As in other virus infections, this is a standard approach for patients with inactive juvenile (psoriatic) arthritis due to the fast effect at restart of TNF-alpha inhibitors post-infection." (PMID 33683393, 2021). "Sphingosine kinase (Sphk1) mediates TNFα-induced arthritis and osteoclastogenesis via TNFα receptor activating factor 2 (TRAF2)." (PMID 34968192, 2021). "There are multiple models of arthritis dependent on increase in TNFα concentration, including the model of CFA-induced arthritis." (PMID 34163464, 2021). "In different animal models of arthritis, the A3AR agonist CF101 exerted significant antirheumatic effects reducing the clinical and histological features of arthritis mainly by a decrease of TNF-α production." (PMID 34299305, 2021). "As a result, delanzomib combined with adalimumab exhibited stronger anti-arthritis activity than a single drug because both drugs synergistically reduced TNF-α level in vivo." (PMID 34880764, 2021). "Resolving arthritis FLS also consistently demonstrated greater metabolic agility in response to inflammatory stimulation with TNFα ex vivo." (PMID 34512657, 2021). "Injections of TNF inhibitors during arthritis increased pro-resolutive markers in bone marrow precursors and joint cells leading to a decrease in arthritis score." (PMID 33889824, 2021). "Blocking IL-17A or TNF along with the depletion of CD4+ T cells produced protective effects against the development of arthritis with modulation of TRAP5b." (PMID 34067675, 2021). "It is suggested that infiltration TNFα-secreting macrophages into joint capsule is a starting point in the onset of arthritis followed by systemic inflammation and progression of the disease." (PMID 34163464, 2021). "The timing of Sost upregulation in another RA model suggests that bone loss markers and an increase in Sost expression are concomitant with expression of TNFα, preceding arthritis onset." (PMID 34502021, 2021). "TNF-α is one of the crucial mediators in the pathogenesis of arthritis, one of the main targets in biological therapy of RA." (PMID 35126351, 2021). "Platelet MPs are reported to be a source of IL-1, IL-6, and tumor necrosis factor-α (TNF-α) and amplify inflammation in arthritis." (PMID 34769139, 2021). "Because IL-23 induces TNF expression and TNF transgenic mice developed chronic arthritis, these investigators attempted to identify the mechanism for IL-23-induced arthritis with regards to IL-17A, TNF, and CD4+ T cells." (PMID 34067675, 2021). "Recent studies have shown that TNF-α is the most important mediator that alters the cartilage matrix degradation and balance in patients with arthritis and ultimately leads to cartilage degradation." (PMID 34735544, 2021). "In this study, we confirmed the inhibiting activity of peptide 17.1 and demonstrated that its shortened fragment, peptide 17.1A, can be also characterized as an inhibitor of TNFα-dependent arthritis." (PMID 34163464, 2021).